IKBKG (inhibitor of nuclear factor kappa B kinase regulatory subunit gamma)
Diseases named in the same sentence as IKBKG in open-access papers (continued):
Sharing a sentence is not in itself a finding about the gene and the disease.
Hepatic steatosis (1 paper, 2009). Steatosis is a term used to denote lipid accumulation within hepatocytes. "In contrast, IKBKG, also known as NF-κB essential modulator (NEMO), is required for the activation of the NF-κB complex by proinflammatory stimuli, and it has recently been recognized as suppressor of hepatic steatosis, possibly through the negative interaction with PPARs." (PMID 19680557, 2009).
Hypoglycemia (1 paper, 2022). A decreased concentration of glucose in the blood. "We identified two additional variants in IKBKG: the first, p.X420Yext27, in a male infant (K1) with lethargy, hypotonia, oligohydramnios, hypoglycemia, progressive encephalopathy, and respiratory failure, was an identical variant to the variant seen in F12 and was apparently maternally inherited." (PMID 36210382, 2022).
ischemia (1 paper, 2025). A hypoperfusion of the BLOOD through an organ or tissue caused by a PATHOLOGIC CONSTRICTION or obstruction of its BLOOD VESSELS, or an absence of BLOOD CIRCULATION. "We found that miR-125a-5p significantly suppresses ischemia-induced inflammation and neuronal death by targeting IKBKG." (PMID 40585973, 2025).
Klinefelter syndrome (1 paper, 2024). A sex chromosome disorder caused by the presence of an extra X chromosome in the male karyotype. "Hemizygous variants with loss of IKBKG/NEMO function are lethal in males, while IKBKG/NEMO variants with partial suppression of protein function are observed in heterozygous females with IP, as well as in males with the mosaic form of the disease or XXY genotype (Klinefelter syndrome)." (PMID 39086952, 2024).
learning disability (1 paper, 2014). A group of disorders that affect a person's ability to learn or process specific types of information which is in contrast to his/her apparent level of intellect. "In conclusion, the present study enrols learning disability amongst the CNS defects associated to IP disorder and supports a role of the IKBKG/NEMO gene as a genetic determinant of such a defect." (PMID 24489960, 2014). "Results of this comprehensive evaluation of the molecular and psychoneurological aspects of IP make it possible to place “learning disabilities” among the CNS manifestations of the disease and suggest that the IKBKG/NEMO gene is a genetic determinant of this CNS defect." (PMID 24489960, 2014).
lymph node metastases (1 paper, 2024). "It was found that neither the occurrence of lymph node metastases nor their number correlated with the level of IKBKG gene expression." (PMID 39337357, 2024).
mycobacterial infections (1 paper, 2025). "Moreover, specific missense IKBKG variants can lead to susceptibility to mycobacterial infections with no developmental defects, in the presence of a normal amount of NEMO mutant protein." (PMID 39860371, 2025).
staphylococcal infection (1 paper, 2025). An infection caused by Staphylococcus. "An increase in susceptibility to pneumococcal and staphylococcal infections has also been found to be linked with broader mutations in IKBKG (NEMO) and NFKB1." (PMID 41510457, 2025).
triple X syndrome (1 paper, 2024). "Overexpression of X-linked genes, such as IKBKG (NEMO), could be caused by the presence of an extra X chromosome in individuals with triple X syndrome." (PMID 39712011, 2024).
tumor (61 papers, 2008 to 2025). "Among these genes, IKBKG encodes nuclear factor κB essential modulator (NEMO), which acts as a tumor repressor in HCC." (PMID 36225557, 2022). "To further elucidate the impact of DDX24 on IKBKG splicing, we examined the splicing of IKBKG in tumor tissues from xenograft models." (PMID 39897555, 2025). "Functional rescue experiments confirm that the long IKBKG isoform-mediated autophagy confers the anti-tumor effects of DDX24 depletion." (PMID 39897555, 2025). "Ratio differences of important immune-related AS events (clualt3p199530 NRG1, clualt5p154454 SH3BP2, clualt5p114936 ACKR3, clualt5p152292 IL15, cluir97910 NFKBIB, and clualt5p204621 IKBKG) between tumor and normal tissues are presented." (PMID 37139238, 2023). "Several members of the canonical NF-κB pathway were in the top list, including RELA, NFKB1, CHUK, IKBKB, IKBKG, and REL, indicating that the canonical NF-κB pathway was closely associated with immune-related DEGs in tumour serum-cultured DCs." (PMID 28350008, 2017). "IKBKG belongs to one of our identified four novel genes coding for kinases, which were correlated to response of tumor cells towards ART." (PMID 20428086, 2010). "To further explore the tumor-suppressive effects of DDX24 depletion in vivo, driven by the increased production of the long isoform of IKBKG, we conducted xenograft mouse experiments using cell lines with simultaneous silencing of DDX24 and IKBKG-L." (PMID 39897555, 2025). "A previous study showed that IKBKG in KIRC could prevent cancer cells from entering apoptosis by regulating HIF, promoting cancer cell survival and tumor metastasis." (PMID 33456463, 2020).
infection (49 papers, 2009 to 2025). The state of being infected such as from the introduction of a foreign agent such as serum, vaccine, antigenic substance or organism. "The results revealed that with increasing infection time, the expression of IKBKG, AKT1, CDC37, MAP3K2, and PKN2 decreased, whereas the expression of MAP3K7 and KRAS2 increased." (PMID 40078537, 2025). "With increasing infection time, the expression levels of IKBKG and KRAS2 increased, whereas the expression levels of MAP3K7, MAP3K2, AKT1, CDC37, and PKN2 decreased." (PMID 40078537, 2025). "On the contrary, inhibitory genes of NF-kappaB activity, e.g. IKBKB, NFKBIB and IKBKG decreased over infection time." (PMID 36544767, 2022). "In 3D4/21 cells, with increasing NS5A infection time, the protein expression of AKT1, IKBKG, CDC37, MAP3K2, and PKN2 decreased, whereas the protein expression of KRAS2 and MAP3K7 increased." (PMID 40078537, 2025). "The situation is further complicated by fluctuations in NEMO protein expression levels upon cell passaging and a slight induction of IKBKG mRNA levels by HAV 3C expression/infection, which might compensate NEMO cleavage to some extent." (PMID 39853114, 2025).
cancer (43 papers, 2011 to 2025). A tumor composed of atypical neoplastic, often pleomorphic cells that invade other tissues. "As a core component of the IKK complex, IKBKG is pivotal in NF-kB activation and has been implicated in both cancer and autophagy." (PMID 39897555, 2025). "Notably, IKBKG was implicated in various cancer to promote tumorigenesis." (PMID 36726781, 2022). "No significant trends were noted between clinical staging and the expression of any genes in the investigated cancers; however, IKBKG gene expression was found to be decreased in the advanced stages of STAD." (PMID 39337357, 2024). "No other significant relationships were found regarding the connection between CHUK, IKBKB, or IKBKG gene expression and cancer type." (PMID 39337357, 2024). "The DNA methylation patterns of core CERGs in the 20 cancer types were also observed, and some of these genes, such as IKBKG and TNFRSF1B, showed consistent hypomethylation." (PMID 38297270, 2024). "Generally, the MEXPRESS database identified a weak negative correlation between the mRNA expression of CHUK, IKBKB, and IKBKG genes and the methylation status of particular CpG islands/dinucleotides in the investigated cancers." (PMID 39337357, 2024). "IKBKB and IKBKG were both upregulated in all examined cancers, while CHUK only presented increased expression in ESCA and STAD." (PMID 39337357, 2024). "Furthermore, other studies, have found that mutations leading to the deletion of gene fragments or loss of IKBKG function were associated with an inhibition of the NF-κB pathway and activation of apoptosis, which could have a protective function against the development of cancer." (PMID 39337357, 2024). "Moreover, ChIP-chip assays yielded a total of 48 genes enriched in at least three of the seven primary samples including genes associated with cell cycle such as ARGHEF2, CCNA2, CDKN2D, GAK2, ORCL6, PCPNP, and TACC1 and genes associated with cancer such as AR, AXIN2, IKBKG, ETS1, PTPN11, and WNT2B." (PMID 23300998, 2013). "The correlation between CHUK, IKBKB, IKBKG, and the overall survival (OS) of patients with COAD, ESCA, READ, and STAD cancer was assessed using the KM plotter database." (PMID 39337357, 2024). "As such, changes in these genes may affect cancer development; however, the role of the CHUK, IKBKB, and IKBKG genes is not fully known." (PMID 39337357, 2024). "GEPIA analysis indicated lower expression of the IKBKB and IKBKG genes in all examined GI cancers compared to normal cells; however, in most cancers, the difference was not statistically significant." (PMID 39337357, 2024). "Specifically, melatonin could shift the splicing of IKBKG to increase the production of NEMO long isoform, thereby inhibiting cancer cell proliferation." (PMID 36225557, 2022). "Interestingly, NEMO (IKBKγ) (FC 1.11), IKBKB (FC 0.94), NFκB1 (FC 0.92) and RELA (FC 1.12) were only slightly changed in carcinoma tissue compared to normal mucosa." (PMID 29188362, 2018).
bacterial infections (13 papers, 2015 to 2025). "Almost a third of patients with IKBKG mutations had concomitant infections, with bacterial infections being the most common (79.7%), followed by viral (14.5%), fungal (5.1%), and parasitic (0.7%) infections." (PMID 40612668, 2025). "Genetic deficiencies of key mediators of the innate immune response, autosomal recessive IRAK4, and X-linked recessive IKBKG (encoding for NEMO) deficiencies, underlie pyogenic bacterial infection with impaired interleukin-6 (IL-6) production and C-reactive protein (CRP) production." (PMID 32067109, 2020). "Female carriers of hypomorphic IKBKG variants with non-skewed lyonization are at risk to produce too much NEMO-∆ex5 that they develop NDAS, and in turn too little amount of full-length protein to prevent bacterial infections." (PMID 39264518, 2024). "Furthermore, subgroups of individuals with NEMO deficiency resulting from IKBKG mutations do not demonstrate evidence of AED and may exhibit susceptibility to pyogenic bacterial infection without apparent vulnerability to mycobacteria or viruses." (PMID 25886387, 2015).
genetic disease (4 papers, 2016 to 2022). "As IKBKG is the only gene responsible for IP, these rates are low in comparison with other genetic diseases, even when taking into consideration that the IKBKG locus has a complex genomic structure." (PMID 33085210, 2020).
respiratory diseases (1 paper, 2024). "Next, complementary analyses identified nine DMGs (LTA, STAT3, IKBKG, IRAK1, NOD2, TLR2, TNFRSF1A, and IKBKB) that might be involved in the immune response of XJB cattle infected with respiratory diseases." (PMID 38732144, 2024).
retinopathy (1 paper, 2023). "It is assumed that the pathogenesis of retinopathy in IP is similar to the pathogenesis of CNS changes, that is, that the apoptosis of vascular cells with IKBKG mutation is its basis." (PMID 37046518, 2023).
skeletal dysplasia (1 paper, 2007). Any Mendelian diseases that affects growth and development of the skeleton. "Mutations in the genes encoding some of the molecules in these pathways, including RPS6SKA3, LIFR, TNFRSF11A and IKBKG, have been associated with human skeletal dysplasias, again suggesting that the remaining genes may also serve critical roles in endochondral ossification." (PMID 17565682, 2007).
IKBKG also shares sentences with these, for which no sentence is quoted: atherosclerosis (11 papers); Anhidrotic ectodermal dysplasia (7); diabetes (6); liver disease (6); lymphedema (6); melanoma (6); prostate carcinoma (6); chronic hepatitis (5); osteosarcoma (5); psoriasis (5); agammaglobulinemia (4); chronic granulomatous disease (4); inflammation (4); ovarian carcinoma (4); Stroke (4); X-linked anhidrotic ectodermal dysplasia (4); Arthritis (3); autoimmune disease (3); eosinophilia (3); gastric cancer (3); glioma (3); liver fibrosis (3); neurodegenerative disease (3); skin inflammation (3); X-linked agammaglobulinemia (3); acute myeloid leukemia (2); Alzheimer disease (2); ataxia telangiectasia (2); Autoimmunity (2); B-cell lymphoma (2).
A further 170 diseases each share a sentence with IKBKG in 2 papers or fewer.